TRBV2 (T cell receptor beta variable 2)
Description:
V region of the variable domain of T cell receptor (TR) beta chain that participates in the antigen recognition. Alpha-beta T cell receptors are antigen specific receptors which are essential to the immune response and are present on the cell surface of T lymphocytes. Recognize peptide-major histocompatibility (MH) (pMH) complexes that are displayed by antigen presenting cells (APC), a prerequisite for efficient T cell adaptive immunity against pathogens. Binding of alpha-beta TR to pMH complex initiates TR-CD3 clustering on the cell surface and intracellular activation of LCK that phosphorylates the ITAM motifs of CD3G, CD3D, CD3E and CD247 enabling the recruitment of ZAP70. In turn ZAP70 phosphorylates LAT, which recruits numerous signaling molecules to form the LAT signalosome. The LAT signalosome propagates signal branching to three major signaling pathways, the calcium, the mitogen-activated protein kinase (MAPK) kinase and the nuclear factor NF-kappa-B (NF-kB) pathways, leading to the mobilization of transcription factors that are critical for gene expression and essential for T cell growth and differentiation. The T cell repertoire is generated in the thymus, by V-(D)-J rearrangement. This repertoire is then shaped by intrathymic selection events to generate a peripheral T cell pool of self-MH restricted, non-autoaggressive T cells. Post-thymic interaction of alpha-beta TR with the pMH complexes shapes TR structural and functional avidity.
Synonyms: TCRBV22S1A2N1T; TCRBV2S1
Gene: T-cell receptor variable (V) gene on chromosome 7 (142,300,924 to 142,301,432, forward strand). Ensembl gene ENSG00000226660.
Subcellular location: Cell membrane
Gene Ontology:
Biological process: cell surface receptor signaling pathway
Cellular component: plasma membrane
Homologues: Orthologues: mouse Trbv3 (69% identical). Paralogues in human: TRBV7-2 (51% identical), TRBV7-9 (51% identical), TRBV7-3 (50% identical), TRBV7-6 (50% identical), TRBV11-1 (49% identical), TRBV11-2 (49% identical), TRBV17 (49% identical), TRBV7-7 (49% identical), TRBV12-3 (46% identical), TRBV12-4 (46% identical), TRBV12-5 (46% identical), TRBV7-1 (45% identical), and 39 more.
Diseases named in the same sentence as TRBV2 in open-access papers:
TRBV2 is named in the same sentence as 9 diseases in open-access papers, as found by Europe PMC text mining. Sharing a sentence is not in itself a finding about the gene and the disease. The quoted sentences say what the papers report.
COVID-19 (2 papers, 2024 to 2025). A disease caused by infection with severe acute respiratory syndrome coronavirus 2. "The expression of genes such as TRDV2, TRVD1, TRAV38-1, TRBV3-1, TRAV13-1, and TRBV2 was among the 15 most decreased in all data of severe COVID-19." (PMID 38262689, 2024).
autoimmune disease (1 paper, 2021). A disorder resulting from loss of function or tissue destruction of an organ or multiple organs, arising from humoral or cellular immune responses of the individual to their own tissue constituents. "However, the segments associated with autoimmune diseases, like TRBV2, TRBV6, and TRBV8.2, were not upregulated in WAS chimeric mice." (PMID 35116029, 2021).
cutaneous T-cell lymphoma (1 paper, 2025). "Changes in the expression of TRBV5-7 and TRBV2 have been noted in human patients with early-stage to advanced-stage mycosis fungoides, a type of cutaneous T-cell lymphoma that mainly affects the hair follicle." (PMID 40725390, 2025).
Löfgren's syndrome (1 paper, 2020). "Using deep sequencing approaches, our group recently demonstrated that TRAV12-1 preferentially pairs with TCRβ variable region (TRBV) 2 in BAL CD4+ T cells from Löfgren's syndrome patients and that TRAV12-1 and TRBV2 are the most expanded variable regions relative to control subjects." (PMID 32256501, 2020).
sarcoidosis (1 paper, 2020). Sarcoidosis is a multisystemic disorder of unknown cause characterized by the formation of immune granulomas in involved organs. "In an acute form of sarcoidosis, there are expansions of specific TRAV12-1/TRBV2 T cell receptors expressed on BAL CD4+ T cells, indicating that these T cells are trafficking to and expanding in the lung in response to common antigens." (PMID 32256501, 2020).
infection (1 paper, 2025). The state of being infected such as from the introduction of a foreign agent such as serum, vaccine, antigenic substance or organism. "Infection with ALV-J did not induce any changes in the TRBJ gene usage in the M-line chickens, although an increased usage of TRBV1 and a decreased usage of TRBV2 were observed compared to the control M-line." (PMID 39943104, 2025).
TRBV2 also shares sentences with these, for which no sentence is quoted: cancer (1 paper); mycosis fungoides (1); tumor (1).